PTK6 (protein tyrosine kinase 6)
Diseases named in the same sentence as PTK6 in open-access papers (continued):
Sharing a sentence is not in itself a finding about the gene and the disease.
pancreatic cancer (8 papers, 2014 to 2025). "(1.6/1.7-fold increase in Panc1, and 1.4/1.6 in MIAPaCa2, for migratory and invasive potential, respectively, p<0.05) These findings suggest that PTK6 expression in pancreatic cancer is associated with its cellular migratory and invasive potential." (PMID 24788754, 2014). "Instead, ERK1/2 emerged as a key downstream mediator of PTK6-associated signal which regulates pancreatic cancer invasion." (PMID 24788754, 2014). "Subsequent studies have shown increased expression and activation of PTK6 in various cancers, including breast, prostate, colorectal, and pancreatic cancers." (PMID 40809015, 2025). "PTK6 has been suggested to promote pancreatic cancer cell migration and invasion by activating ERK1/2." (PMID 34884984, 2021). "Our key finding in this study is that PTK6 overexpression increases cellular migration and invasion and that PTK6 gene silencing, in contrast, decreases them in pancreatic cancer cells." (PMID 24788754, 2014). "Immunostaining for PTK6 in pancreatic cancer tissues from 9 patients demonstrated that PTK6 was highly expressed in 4 patients (44%), mildly to moderately expressed in 2 patients (22%), and not expressed at all in 3 patients (33%)." (PMID 24788754, 2014). "It is therefore less likely that these molecules play a role in mediating the effect of PTK6 on cellular migration/invasion in pancreatic cancer." (PMID 24788754, 2014). "It was interesting to note that while PTK6 expression was uniformly undetectable in adjacent histologically normal pancreatic duct epithelial cells, PTK6 levels varied substantially among the pancreatic cancers we studied." (PMID 24788754, 2014). "Besides, silencing PTK6 significantly attenuated cellular migration and invasion in pancreatic cancer." (PMID 32537471, 2020). "Another study has shown that PTK6 promotes the migration of pancreatic cancer cells." (PMID 25748447, 2015). "Erb B2 is well known to be overexpressed commonly in pancreatic cancers so this might be a possible mechanism by which forced PTK6 overexpression in pancreatic cancer cells could activates ERK1/2 without ERK5 activity." (PMID 24788754, 2014). "Five pancreatic cancer cell lines expressed PTK6 at varying levels." (PMID 24788754, 2014). "In summary, we demonstrated that PTK6 is expressed aberrantly in pancreatic cancer." (PMID 24788754, 2014). "The potential prognostic value of variation in PTK6 in pancreatic cancer awaits further study." (PMID 24788754, 2014). "In this study, we evaluated the role of PTK6 on pancreatic cancer cell invasion and explored the downstream signals that might mediate such an effect." (PMID 24788754, 2014). "Our findings suggest that PTK6 regulates invasiveness by activating ERK and raises the possibility that PTK6 may be an important new molecular target to improve the efficacy of therapy for pancreatic cancer." (PMID 24788754, 2014). "ERK1/2 therefore emerged as the candidate for the mediator of PTK6-regulated cellular motility in pancreatic cancer and we accordingly sought to determine whether the effects of PTK6 on cellular migration and invasion depend on ERK1/2 activity." (PMID 24788754, 2014). "Therefore in this study, we evaluated the functional role of PTK6 on pancreatic cancer invasion." (PMID 24788754, 2014). "PTK6 may be a novel therapeutic target for pancreatic cancer." (PMID 24788754, 2014). "Further investigation of the PTK6-dependent signaling pathway that drives invasion in pancreatic cancer may highlight the potential prognostic and therapeutic importance of this novel signal in pancreatic cancer." (PMID 24788754, 2014). "In the current study of multiple pancreatic cancer cell lines, most of the molecules that have previously reported to be associated with PTK6 signaling in other cancers did not change in activity by manipulation of PTK6 expression." (PMID 24788754, 2014).
pancreatic cancer (continued). "Furthermore, our results suggest that PTK6 may promote cellular migration and invasion in pancreatic cancer by activating ERK1/2." (PMID 24788754, 2014). "However, the biological role and expression status of PTK6 in pancreatic cancer is unknown." (PMID 24788754, 2014). "We compared PTK6 levels in five established human pancreatic cancer cell lines (BXPC3, Capan1, Hs766T, MIAPaCa2, and Panc1) and pancreatic cancer tissues taken directly from 9 patients who underwent surgical resection." (PMID 24788754, 2014). "Moreover, overexpression of CDH4, PTK6, and TFAP2C re-sensitizes pancreatic cancer cells to gemcitabine." (PMID 36289850, 2022). "PTK6, a non-receptor type tyrosine kinase, was involved in breast, pancreatic cancer and metastatic skin cancer." (PMID 33133157, 2020).
prostate tumor (8 papers, 2011 to 2023). "Vemurafenib inhibited PTK6 activity and oncogenic signaling in prostate cell lines, as well as xenograft prostate tumor growth." (PMID 36228719, 2022). "Targeting PTK6 to the plasma membrane promoted an epithelial mesenchymal transition and increased tumorigenesis of prostate tumor cells." (PMID 36228719, 2022). "In human prostate tumor tissue microarrays, loss of PTEN correlates with increased PTK6 PY342 and poor outcome." (PMID 29142193, 2017). "Previously it was shown that PTK6 is localized to epithelial cell nuclei in normal prostate, but becomes cytoplasmic in human prostate tumors." (PMID 21479203, 2011). "Sam68, as a substrate of PTK6, colocalizes with PTK6 to promote the growth of prostate tumor cells." (PMID 36690663, 2023). "Differences in PTK6 intracellular localization have been observed in prostate tumor cells." (PMID 31278310, 2019). "Prostate tumor cells had a higher PTK6 to ALT-PTK6 ratio than normal prostate cells." (PMID 21479203, 2011). "Activation of PTK6 at the plasma membrane also promotes the epithelial mesenchymal transition (EMT) and survival and metastasis of prostate tumor cells in xenograft models." (PMID 29142193, 2017). "Examination of PTK6 and PTEN in a human prostate tumor tissue microarray demonstrates an inverse correlation between PTK6 activation and expression of PTEN." (PMID 29142193, 2017).
triple-negative breast carcinoma (8 papers, 2015 to 2025). An invasive breast carcinoma which is negative for expression of estrogen receptor (ER), progesterone receptor (PR), and human epidermal growth factor receptor 2 (HER2). "Conversely, other research has shown that MARCH2 can target Snail for ubiquitination and proteasomal degradation, and that PTK6 regulates MARCH2 levels in the context of Snail-mediated EMT in triple-negative breast cancer cells." (PMID 41213909, 2025). "This study suggests that PTK6 promotes tumor development and was associated with poor prognosis in the LNM + group of triple negative breast cancer." (PMID 37932734, 2023). "Since many previous studies have reported that PTK6 promotes tumor cell migration, PTK6 is more likely to promote triple-negative breast cancer metastasis." (PMID 37932734, 2023). "The aim of this study was to investigate the expression of PTK6 in different groups of triple negative breast cancer and its impact on prognosis." (PMID 37932734, 2023). "In contrast, downregulation of PTK6 reversed EMT in triple-negative breast cancer cells and inhibited their growth and migration, but enhanced anoikis in vitro as well as suppressed metastatic ability in vivo through regulation of E-Cadherin." (PMID 34884984, 2021). "Inhibition of PTK6 may be a new approach for the treatment of triple negative breast cancer patients, especially those with metastasis." (PMID 37932734, 2023). "Knockdown of PTK6 expression by shRNA or siRNA in tumor cells leads to significant inhibition of tumor growth, induction of tumor cell apoptosis, and suppression of metastases of triple negative breast cancer, while overexpression of PTK6 promotes cell proliferation." (PMID 29879184, 2018). "Kinase activity of overexpressed PTK6 is also responsible for enhanced cell migration and invasion of MDA-MB-231 triple-negative breast cancer cells." (PMID 26084280, 2015). "PTK6 has also been shown to promote cell proliferation and migration through phosphorylation of Eps8, regulate the expression of E-cadherin through SNAIL protein degradation, promote epithelial mesenchymal transformation and regulate the metastasis of triple-negative breast cancer cells." (PMID 37932734, 2023). "In triple-negative breast cancer, long intergenic non-coding RNA for kinase activation (LINK-A) mediates hypoxia inducible factor 1 subunit alpha (HIF1α) phosphorylation and stabilization by protein tyrosine kinase 6 (BRK) and leucine rich repeat kinase 2 (LRRK2) interaction." (PMID 32429086, 2020).
bladder cancer (7 papers, 2021 to 2025). "PTK6 overexpression was strongly linked to the T classification, the N classification, the grade, the recurrence of bladder cancer, and a poor clinical outcome in patients with the disease." (PMID 36405012, 2022). "Xu and his group reported that when compared to the normal controls, the expression of PTK6 is much higher in bladder cancer tissues." (PMID 36405012, 2022). "PTK6 induced phosphorylation of ETV4 and increased nuclear translocation of ETV4, leading to enhanced metastasis in bladder cancer." (PMID 40777122, 2025).
esophageal squamous cell carcinoma (7 papers, 2013 to 2023). Esophageal squamous cell carcinoma (ESCC) is a type of esophageal carcinoma (EC) that can affect any part of the esophagus, but is usually located in the upper or middle third. "Studies on esophageal squamous cell carcinoma and laryngeal squamous cell carcinoma showed that low PTK6 expression was significantly associated with low 5-year OS rates for patients." (PMID 27311570, 2016). "Downregulated expression of PTK6 correlates with the poor survival of esophageal squamous cell carcinoma." (PMID 36690663, 2023). "In contrast, PTK6 played an inhibitory role in the regulation of the proliferation, differentiation, and migration of nasopharyngeal carcinoma and esophageal squamous cell carcinoma." (PMID 34551797, 2021). "The downregulation of protein tyrosine kinase 6 (PTK6) in esophageal squamous cell carcinoma (ESCC) has been described." (PMID 27053248, 2016). "However, another study showed that PTK6 expression was downregulated in laryngeal squamous cell carcinoma and esophageal squamous cell carcinoma tissues, and low expression levels of PTK6 predicted short survival." (PMID 34721517, 2021). "In contrast, PTK6 may be an important tumor suppressor in various human cancers, such as human laryngeal squamous cell carcinoma and esophageal squamous cell carcinoma." (PMID 26709519, 2015). "However, in other tumors, including nasopharyngeal carcinoma and esophageal squamous cell carcinoma, PTK6 may play an important anti-oncogenic role by regulating cell proliferation, differentiation, and migration." (PMID 27311570, 2016).
colorectal cancer (6 papers, 2021 to 2023). A primary or metastatic malignant neoplasm that affects the colon or rectum. "PTK6 plays a tumor suppressor role in colorectal cancer cells by antagonizing the epithelial-mesenchymal transition (EMT) pathway." (PMID 36690663, 2023). "Here, we discuss the current understanding of the function of PTK6 in normal intestinal cells compared with colorectal cancer cells." (PMID 37509364, 2023). "In contrast, PTK6 plays an inhibitory role in the development of colorectal cancer and nasopharyngeal carcinoma." (PMID 36690663, 2023). "We review existing PTK6 targeting therapeutics and explore the possibility of PTK6 inhibitory therapy for colorectal cancer." (PMID 37509364, 2023). "PTK6 phosphorylates multiple substrates, including signal transduction proteins, RNA binding proteins, and transcription factors, many of which are involved in key colorectal cancer pathways." (PMID 37509364, 2023). "The same study reported that TCGA Colorectal Cancer dataset analysis, comparing tumor with paired normal tissue, clearly demonstrated PTK6 overexpression in colon adenocarcinomas relative to adjacent normal tissue, which is similar to the unpaired TCGA/GTex comparison." (PMID 37509364, 2023). "However, PTK6 appears to promote apoptosis in colorectal cancer, human osteosarcoma U2OS cells and astrocytes, thereby inhibiting cell division and proliferation." (PMID 37932734, 2023). "We propose that targeting PTK6 therapeutically in colorectal cancer could increase cancer cell sensitivity to standard chemotherapy treatment." (PMID 37509364, 2023). "In this review, we explore a potential role for PTK6 in colorectal cancer." (PMID 37509364, 2023). "Interacting with JAK2 and phosphorylating it to promote the JAK2/STAT3 pathway is one way that PTK6, and particularly phosphorylated PTK6, might enhance the stemness of colorectal cancer cells." (PMID 36405012, 2022). "PTK6 is overexpressed in colorectal tumors vs. normal tissue and activates WNT signaling when localized to the membrane in colorectal cancer cells." (PMID 37509364, 2023). "However, the importance of PTK6 in colorectal cancer remains unclear." (PMID 37509364, 2023).
invasive breast carcinoma (6 papers, 2007 to 2022). A carcinoma that infiltrates the breast parenchyma. "Breast tumour kinase, also known as protein tyrosine kinase 6 (Brk/PTK6) is overexpressed in a high proportion of invasive breast cancers, and represents a possible target for therapeutic intervention." (PMID 35327957, 2022). "In contrast, total PTK6 and PTK6 P-Y342 were localized in nuclei in high-grade LCIS, a premalignant condition that indicates risk for developing invasive breast cancer." (PMID 25153721, 2014). "In this study, we used the PLA technique to show for the first time ever that PTK6 forms protein complexes with HER2 in paraffin tissues from invasive breast carcinomas." (PMID 20700126, 2010). "Protein tyrosine kinase 6 (PTK6; breast tumour kinase) is overexpressed in up to 86% of the invasive breast cancers, and its association with the oncoprotein human epidermal growth factor receptor 2 (HER2) was shown in vitro by co-precipitation." (PMID 20700126, 2010). "We show that PTK6 protein expression is a prognostic marker for disease-free survival, on the basis of the data from a cohort of 426 invasive breast cancer cases." (PMID 18781181, 2008). "We investigated the protein expression of the HER1–HER4 receptors and of the PTK6 in invasive breast carcinomas with long-term follow-up, and found a previously undescribed time-dependent prognostic relevance of PTK6 using multivariate analysis." (PMID 17299391, 2007). "Although the sample size was limited, these data suggest that PTK6 activation at the membrane as measured by P-Y342 may be most apparent in invasive breast cancers." (PMID 25153721, 2014). "Eighty primary invasive breast carcinomas were analyzed using the PLA technique, using primary antibodies against both HER2 and PTK6 proteins." (PMID 20700126, 2010).
laryngeal squamous cell carcinoma (6 papers, 2013 to 2023). A squamous cell carcinoma that arises from the larynx. "In patients with laryngeal squamous cell carcinoma, low expression of PTK6, as detected by IHC, was associated with short OS and DFS." (PMID 27311570, 2016). "Patients with laryngeal squamous cell carcinoma who had high expression levels of PTK6 had an overall and disease-free survival rate that was more favorable." (PMID 36405012, 2022). "However, high PTK6 expression was associated with good OS and DFS in laryngeal squamous cell carcinoma patients." (PMID 37932734, 2023). "However, little was known about PTK6 expression and its clinicopathological significance in human laryngeal squamous cell carcinoma (LSCC)." (PMID 23497344, 2013).
hepatocellular carcinoma (5 papers, 2019 to 2023). A malignant tumor that arises from hepatocytes. "For instance, PSPC1 was recently shown to be the contextual determinant of the TGF-β prometastatic switch and PTK6/β-catenin reciprocal oncogenic nucleocytoplasmic shuttling during hepatocellular carcinoma (HCC) progression." (PMID 34340703, 2021). "Here, the authors demonstrate that PSPC1 is the contextual determinant of the oncogenic switch of PTK6/β-catenin subcellular localizations to drive metastasis of hepatocellular carcinoma cells via a PSPC1/PTK6/β-catenin signaling." (PMID 31844057, 2019). "PSPC1 is also a substrate of protein tyrosine kinase 6 (PTK6) but sequestered PTK6 in the nucleus and abolished the PSPC1 oncogenic functions in human hepatocellular carcinoma (HCC) cells." (PMID 32570949, 2020).